CD44 (CD44 molecule (IN blood group))
Diseases named in the same sentence as CD44 in open-access papers (continued):
Sharing a sentence is not in itself a finding about the gene and the disease.
breast carcinoma (continued). "However, another study revealed that immobilised but not soluble HA enhanced co-localisation of CD44 and the receptor for hyaluronic acid-mediated motility (RHAMM), contributing to the aggressive and invasive phenotype in breast cancer cell lines." (PMID 34944493, 2021). "In vitro studies on breast cancer cells indicated that lipoplex cytotoxicity was not modified by the presence of the HA-DOPE conjugate, but its presence increased the transfection efficiency on CD44+ MDA-MB-231 cells compared to the CD44- MCF-7 line." (PMID 34683830, 2021). "In this review, we focus upon the biology of CD44 and RHAMM because—unlike LYVE1, STAB2/HARE, and LAYN—these receptors have been studied in detail in the context of cutaneous wound repair and breast cancer and because they are well characterized to directly bind to HA." (PMID 34827550, 2021). "In contrast to miR-7 expression, the relative expression levels of XIST, RELA, CD44, slug, and ESA were significantly higher in breast cancer tissues than in adjacent noncancerous tissues (p = 0.0486, p = 0.038, p = 0.0297, p = 0.0420, and p = 0.0434, respectively)." (PMID 32143670, 2020). "Further, we downloaded RNA‐Seq data from breast cancer patients from TCGA‐breast cancer database and found that the expression level of SPRY4‐IT1 was significantly higher in patients with CD44+/CD24‐ breast cancer (n = 237) than those without CD44+/CD24− (n = 872)." (PMID 31736268, 2020). "Whether ALDH-positive sorted cells indeed resemble a pure CSC population is not clear because there are various CSC markers, such as CD44 +/CD24 –, which are also known as indicators of CSCs in breast cancer." (PMID 30845764, 2019). "Herein, we confirmed that miR-29a levels were not only increased in MCF-7 spheroid cells, CD44+/CD24− MCF-7 cells (BCSCs) and MDA-MB-231 cells compared with MCF-7 cells, but also in breast cancer tissues compared with corresponding distal non-cancerous tissues." (PMID 30792382, 2019). "However, we observed no significant change in the total CD44 expression level by SALL4 knockdown, indicating that SALL4 does not regulate CD44 transcription in basal‐like breast cancer cells." (PMID 29356399, 2018). "Flow cytometry data showed that CXCL1 treatment did not increase CD44+/CD24- or aldehyde dehydrogenase assays (ALDH+) in the MDA-MB-231 and MCF-7 breast cancer cell lines, indicating that CSC-enhancing effects may not explain CXCL1-induced metastasis." (PMID 30158589, 2018). "We observed the expression of CD44, CD24 and ALDH1 in both the primary tumor and the metastases, indicating that these markers did not disappear during the development and metastasis of breast cancer." (PMID 29062075, 2017). "We found that sE-selectin promoted migration and shear-resistant adhesion of CD44+/high breast cancer cell lines (MDA-MB-231 and MDA-MB-468) to non-activated human microvessel endothelial cells (ES-HMVECs), but not of CD44-/low breast cancer cell lines (MCF-7 and T-47D)." (PMID 27220365, 2016). "Additional studies revealed an increase in CD44 expression in the DTCs generated from melanoma cell line MDA-MB-435 and murine ovarian cell lines, 4306 and 4412, suggesting that this phenomenon is not restricted only to breast cancer." (PMID 25669750, 2015). "In support of this hypothesis, it has been shown that CD44- Du145 prostate cells produced CD44+ cells in vitro, and in the MCF-7 breast cancer cell line, the sorted non-SP cells gave rise to SP cells." (PMID 24884875, 2014). "Notably, in breast cancer, the absence of CD24 combined with the presence of CD44 and EpCAM (CD24−CD44+EpCAM+) appears to be critical for the identification of breast CSCs." (PMID 24955581, 2014).
breast carcinoma (continued). "In an attempt to isolate and understand tumorigenic from non-tumorigenic breast cancer cells, Al-Hajj and colleagues used antibodies against CD24 (Heat stable antigen/HAS/BA-1) and CD44 (H-CAM/Pgp-1) to separate heterogeneous cell types in patient-derived xenografts grown in immune-compromised mice." (PMID 25080108, 2014). "Moreover, a large proportion of DTCs in breast cancer patients display stem cell-like features, such as ALDH1 positivity or presence of CD44 and absence of CD24." (PMID 24099325, 2013). "A low proportion of breast cancer cells present in LNs may also result in the absence of specific binding with CD326 monoclonal antibody and in turn, the accuracy of detecting CD44+CD24-/low cell contents in SLN was reduced." (PMID 23046710, 2012). "Other studies have also demonstrated an association between BRCA1 hereditary breast cancer and the presence of CD44+/CD24- cells, whereas our study points to the relationship between BRCA1 and CSC marker CD44 in unselected breast cancer patients rather than only in hereditary breast cancer patients." (PMID 23508738, 2011). "In 2003, Clarke and colleagues demonstrated that a highly tumorigenic subpopulation of BCSCs, expressing CD44+CD24- surface marker in clinical specimen, had the capacity to form tumors with as few as one hundred cells, whereas tens of thousands of the bulk breast cancer cells did not." (PMID 20569497, 2010). "Furthermore, regardless the proportion of T-ICs in the primary tumors or the breast cancer lines, adriamycin or epriubicin significantly increased the apoptosis of non-CD44+/CD24−cells but not that of CD44+/CD24− cells determined by Annexin V staining." (PMID 21187973, 2010). "However, the possibility that SLUG participates in CD44/CD24 phenotypic changes has not been investigated, although its upregulation in basal breast cancers and mammospheres has been reported recently." (PMID 20691079, 2010). "Although the MCF-7 cell line has a luminal epithelial-like phenotype and lacks a CD44+/CD24- subpopulation, we obtained MCF-7-14 cells of opposite migratory and invasive capabilities from MCF-7 cells and developed a novel model for breast cancer metastasis without requiring constitutive EMT." (PMID 20696077, 2010). "Taken together, these results suggested that CD44+/CD24−/low and ALDH may not be universal markers to identify and enrich highly tumorigenic stem cells from all breast cancers." (PMID 20027313, 2009). "Not all basal-like tumors and very few HER2+ tumors, however, contain CD44+/CD24- cells, emphasizing that a putative tumorigenic ability may not be confined to cells of this phenotype and that other breast cancer stem cell markers remain to be identified." (PMID 18559090, 2008). "Indeed, OPG upregulation promoted the pro-metastatic processes EMT and stemness in the non-carcinogenic (MCF-10A) and luminal breast cancer (T-47D, MCF-7) cells, through upregulating the mesenchymal (N-cadherin, SNAIL and ZEB1) and stemness (CD44, ALDH1, Nanog, Klf-4 and Sox2) markers." (PMID 39181873, 2024). "However, the results have shown that cisplatin more specifically targeted progenitor cells, rather than the stem breast cancer cells, with the reduction of the population of CD24−/CD44+ and ALDH1A1 MDA-MB-231 cells being at higher folds in tpMDA, compared to tsMDA." (PMID 33919109, 2021). "Given that ABC transporters might not be involved in hyaluronan translocation in breast cancer, whether the aberrant expression of ABCB1 occurs as a result of CD44 upregulation and whether ABCB1 and its SNPs alter the binding activity of CD44 need to be clarified in future studies." (PMID 33801148, 2021). "CD44+/CD24− ratio is particularly enriched in CSCs of triple negative breast cancer (TNBC), a highly aggressive BC subtype defined by the absence of estrogen and progesterone hormone receptors, and of HER2 amplification." (PMID 33785524, 2021).
breast carcinoma (continued). "We also compared the expression levels of miR-29a in 12 pairs of human breast cancer tissues and their corresponding distal non-cancerous tissues, and in a more aggressive breast cancer cell line, MDA-MB-231 cells, which contains high ratio of CD44+/CD24− cells (~80%)." (PMID 30792382, 2019). "In breast cancer, tumor cells capable of forming tumors in immunocompromised mice (i.e., CSC by a functional definition) are identified by the expression of either the enzyme aldehyde dehydrogenase (ALDH) and/or the CD24−/CD44+ phenotype, representing two largely non-overlapping cell populations." (PMID 30788286, 2019). "In order to confirm this, expression levels of IGF2 protein levels in breast cancer cells with or without CD44+Fbs or CD44−Fbs were examined by Western blotting and IGF2 indeed expressed much higher in breast cancer cells cocultured with CD44+Fbs than with CD44−Fbs." (PMID 28523716, 2017). "After two weeks, MDA-MB-231 cells transfected with the control siRNA could generate tumors, while MDA-MB-231 cells transfected with CD44 siRNA or ALDH1 siRNA could not, indicating that the suppression of CD44 and ALDH1 both reduced the tumorigenicity of breast cancer cells." (PMID 29062075, 2017). "To further validate TF expression on CSCs, we also used a CD44-based human CD24 negative CD44 positive (CD24- CD44+) breast cancer stem cell isolation protocol to isolate CD24- CD44+ CSCs from the TNBC line (MDA-MB-231) and patient-derived human breast cancer cells." (PMID 27903969, 2017). "In addition, in the breast carcinomas, how to understand why the RP215-recognized IgG mainly correlated with the basal-like-origin of MDA-MB-231 of BCSC that show CD44+/CD24−/low, but not with the luminal-like breast cancer cell line MCF-7 of BCSC as well as the CD133+ or ALDH1+ BCSC." (PMID 26472025, 2015). "The current study therefore aimed to investigate the effects of CD44 knockdown on the stemness and differentiation of BCSCs in severe combined immunodeficient (SCID) mice in terms of gene expression, cell cycle, and tumorigenesis, in comparison with breast cancer non-stem cells (non-BCSCs)." (PMID 22152097, 2011). "However, transgenic overexpression of SLUG in the luminal type breast cancer cell line, MCF-7, generated cells with a CD44+/CD24+ phenotype, suggesting that basal cell types but not luminal cell types are susceptible to EMT associated acquisition of CD44+/CD24- phenotype." (PMID 20691079, 2010). "Several techniques have been proposed to isolate or enrich for tumorigenic breast cancer stem cells, including (a) culture of cells in non-adherent non-differentiating conditions to form mammospheres and (b) sorting of the cells by their surface phenotype (expression of CD24 and CD44)." (PMID 18541018, 2008). "Furthermore, we also investigated the stimulatory effects of CoCl2 exposure on the BCSC sphere formation, the size of the CD44+/CD24– subpopulation, and the expression of HIF1α and HIF2α with or without HIF2α inhibitor 76 treatment in other liable human breast cancer cell lines such as MDA-MB-231." (PMID 27270657, 2016).
ovarian carcinoma (401 papers, 1995 to 2026). A malignant neoplasm originating from the surface ovarian epithelium. "For instance, enrichment of CD44+ cancer stem cells is linked to therapy resistance, higher recurrence rates, and shorter overall survival in breast and ovarian cancers." (PMID 40940877, 2025). "Our results, consistent with those of other studies, confirm that CD44 overexpression is associated with higher tumor stages and more aggressive histological types of ovarian cancer (OC)." (PMID 40332380, 2025). "A clinical study was conducted to evaluate CD44 splice variant expression in ovarian cancer using both immunohistochemical and serological analyses." (PMID 41440277, 2025). "Overexpression of CD44 is associated with poor prognosis, while its depletion significantly suppresses tumour proliferation in ovarian cancer." (PMID 39125873, 2024). "In several human ovarian cancer models, overexpression of CD44 is linked with cancer cells adhesion to peritoneal mesothelial cells." (PMID 37287910, 2023). "Although CD44 expression is associated with ovarian cancer patients, its role in the patients’ prognosis is controversial." (PMID 36604635, 2023). "CSCs expressing CD44 were demonstrated to be resistant to chemotherapy and associated with poor survival in ovarian cancer in many studies." (PMID 38201468, 2023). "In the case of ovarian cancer tumors, it has been reported that elevated levels of CD44- and CD133-positive cells were associated with chemotherapy-resistant patients and were present in metastatic and recurrent tumors." (PMID 37958844, 2023). "The presence of CD44 is associated with metastatic and recurrence capacity of ovarian cancer and poor overall survival." (PMID 37958844, 2023). "CD44 was proven to be associated with drug resistance and the tumor metastasis of ovarian cancer in studies." (PMID 37046797, 2023). "In advanced epithelial ovarian cancers, overexpression of CD44 is associated with shorter overall and progression-free survival times due to its promoting effect on both chemoresistance and recurrence of the disease." (PMID 36768723, 2023). "The research described in the literature shows that exosomes secreted from highly metastatic ovarian cancer cells can promote migration and invasion in less metastatic ovarian cancer cells, which is associated with the expression of the CD44 gene." (PMID 36012171, 2022). "In the present study, and in line with these data, higher CD44 mRNA levels were detected in those samples displaying ovarian cancer-cell-associated HA deposition compared to those with a stromal HA pattern." (PMID 36428513, 2022). "As an extensively distributed cell surface marker, CD44 is implicated in the pathogenesis and progression of many cancerous cells, including ovarian cancer cells." (PMID 36789687, 2022). "Hyaluronic acid (HA) is another major ECM protein that binds the adhesion molecule CD44 and has been implicated in ovarian cancer metastasis; increased levels have been associated with poor ovarian cancer outcome." (PMID 36494669, 2022). "In this study, we developed a codon-optimized third-generation CAR to specifically target CD44, a marker widely expressed on ovarian cancer cells and associated with CSC-like properties and intraperitoneal tumor spread." (PMID 34680456, 2021). "Although CD44 can be detected in serum from ovarian cancer patients, it has not been widely tested as a diagnostic biomarker, but rather as a marker of ovarian cancer stem cells." (PMID 33413078, 2021). "OCSCs isolated from the OVCAR-3 ovarian cancer cell line, expressing CD44+ and CD117+ markers that have been associated with chemo-resistance, inhibited growth after treatment with salinomycin and paclitaxel." (PMID 34439332, 2021). "Previous studies have demonstrated that CD44–hyaluronic acid binding is associated with the peritoneal adherence of ovarian carcinoma cells in vitro." (PMID 33807420, 2021).
ovarian carcinoma (continued). "In a recent meta-analysis, overall CD44 expression in ovarian cancer was associated with a high TNM stage and a poor 5 year overall survival." (PMID 32154167, 2020). "We evaluated the expression of mucin-1 (MUC1), cytokeratin 8/18 (CK 8/18) and Wilms’ tumor 1(WT-1), all diagnostic markers of ovarian cancer, and vimentin and CD44 were also analyzed." (PMID 32392708, 2020). "The screening of three ovarian cancer derived cell lines showed SK-OV-3 cells overexpressing CD44 while CD44 expression in OVCAR-3 and OVK18 cells was less or deficient." (PMID 30818864, 2019). "This occurs via an exosome conditioned pathway, whereby ovarian cancer exosomes transfer CD44 to peritoneal mesothelium causing its physical barrier to be cleared." (PMID 31409361, 2019). "More interestingly, there is also research showing that the expression of CD44 splice variant and the survival of ovarian cancer is site dependent." (PMID 31497537, 2019). "Although the association of CD44 expression with the survival of ovarian cancer patients has been widely investigated, the role of CD44 in the prognosis of ovarian cancer remains controversial." (PMID 31497537, 2019). "In ovarian cancer, increased density of CD44-positive cells was shown to be associated with chemotherapy resistance." (PMID 30018258, 2018). "In a previous study, our team found that patients with epithelial ovarian cancer with high ALDH1 expression were associated with CD44 expression, drug resistance, and poor clinical outcome." (PMID 30372483, 2018). "A meta-analysis was then performed to clarify the association between CD44 expression and clinical outcomes of ovarian cancer patients." (PMID 28070170, 2017). "Our findings demonstrate that CD44 expression is associated with a higher tumor TNM stage among ovarian cancer patients." (PMID 28070170, 2017). "Our data reveal that CD44-positive expression in ovarian cancers were significantly associated with a high TMN stage (pooled OR = 2.11, 95% CI 1.26–3.53, P = 0.004) and poor 5-year overall survival (RR = 1.42, 95% CI 1.01–2.00, P = 0.05)." (PMID 28070170, 2017). "In the present study, we performed a systematic review and meta-analysis of the published literature to examine the association of the expression of CD44 or its isoforms with the clinicopathological features and the prognosis of ovarian cancer patients." (PMID 28070170, 2017). "Here, we summarized the pooled data from these studies to increase the statistical power and better evaluate the prognostic values of the expression status of CD44 and its variants in ovarian cancer." (PMID 28070170, 2017). "Pan-CD44 expression is associated with a better prognosis in ovarian cancer, though some other isoforms of CD44 are associated with a poorer prognosis." (PMID 27590006, 2016). "In order to clarify the initial immunohistochemistry results, follow-up analysis were performed to analyze the association of CD44 expression and ovarian cancer progression and prognosis." (PMID 25823654, 2015). "CD44, a cell surface glycoprotein, has been increasingly implicated in the pathogenesis and progression of epithelial ovarian cancer, the deadliest gynecologic malignancy in women." (PMID 26569327, 2015). "The interaction between CD44 and Oct4 has previously been described in squamous cell tumours, and EpCAM and CD44 have previously been implicated in malignant ovarian tumours." (PMID 26260289, 2015). "Coupling of the stem cell marker CD44 with the embryonic stem cell marker Nanog has been shown to be associated with the activation of STAT3 in ovarian cancer cells." (PMID 24782986, 2014). "In the current study, we analyzed drug-resistant clinical ovarian carcinoma samples and found that that Lewis y antigen and CD44 were associated with ovarian carcinoma drug resistance." (PMID 23468946, 2013).